CTSB (cathepsin B)
Diseases named in the same sentence as CTSB in open-access papers (continued):
Sharing a sentence is not in itself a finding about the gene and the disease.
infection (continued). "Furthermore, OM-ALI cells expressed genes for all the characteristic proteins that are important for viral entry and infection, such as TMPRSS-2, CTSB, CTSL, NRP-1, BSG, and furin." (PMID 38098019, 2023). "In the lung cultures, where both TMPRSS2 and Cathepsin B/L are expressed, providing the virus with the ability to fuse both at the cell surface and in endosomes, hydroxychloroquine did not inhibit the infection significantly." (PMID 34608167, 2021). "This study also reveals that cathepsin B protease is important for the CHIKV-pseudotyped vector infection independent of the viral entry pathway." (PMID 32635194, 2020). "Cathepsin B overexpression may more efficiently activate the CHIKV E protein fusogenicity and enhance the infection than control cells." (PMID 32635194, 2020). "Apilimod also had no apparent direct effect on the activity of cathepsin B and L, in contrast to EST, a known inhibitor of cathepsin B, H, and L. Several cationic amphiphilic drugs such as U18666A that block EBOV entry and infection induce cholesterol accumulation in endolysosomes." (PMID 28403145, 2017). "We have previously shown that the Schistosoma mansoni gut-derived cysteine peptidase, cathepsin B1 (SmCB1), administered without adjuvant, elicits protection (>60%) against challenge infection of S. mansoni or S. haematobium in outbred, CD-1 mice." (PMID 28346516, 2017). "The effect of CTSB and vimentin to viral protein expression were confirmed by HCV JFH1 infection." (PMID 26544179, 2015). "The HIV-1 particles could be degraded predominantly by cathepsin B after the viral particles are internalized into endosomes, reducing the CD4-independent infection." (PMID 21541353, 2011). "Cystatin C neither inhibited cathepsin B activity nor enhanced the CD4-independent vector infection in 293T cells, probably because the cathepsin B activity of 293T cells was originally low." (PMID 21541353, 2011). "The cathepsin B overexpression significantly inhibited the CD4-independent vector infection, but did not the CD4-dependent infection." (PMID 21541353, 2011). "Interestingly, we observed partial retention of cathepsin B during infection with a strain lacking the effector CvpB (also referred to as Cig2, encoded by gene CBU_0021)." (PMID 40274809, 2025). "In C2C12 myotubes, CTSB could promote the process of TNF-α post-translation and contribute to its synthesis in response to LPS stimulation, which resulted in a host immunological response to infections." (PMID 40422803, 2025). "For instance, CTSB could promote TNF-α post-translational processing and contribute to its synthesis in response to LPS stimulation, which results in the host’s immunological response to infections." (PMID 40422803, 2025). "In summary, we show that the tested 3CLpro inhibitors have anti-coronavirus (SARS-CoV-2 and MERS-CoV) protease and cathepsin B/L activities and inhibitor 11d significantly enhances survival of mice fatally infected with SARS-CoV-2 or MERS-CoV when treatment started 1 day post infection." (PMID 38126789, 2024). "As lysosomal cathepsin B is involved in NLRP3 inflammasome activation, we examined whether cathepsin B activity contributes to the elevated NLRP3 inflammasome formation and pyroptosis during infection." (PMID 37457695, 2023). "For instance, when 293T cells expressing human ACE2 but not TMPRSS2 were infected with SARS-CoV in the presence of 25 mM NH4Cl, which prevents endosomal acidification and hence blocks Cathepsin B/L, the extent of infection reduced ~40-fold over that in the absence of NH4Cl." (PMID 33290397, 2020). "When we used low, medium or high mean expression levels of Cathepsin B/L in our calculations, with the TMPRSS2 expression level unaltered, we found that the extent of infection increased in the absence of drugs from ~2960 cells/ml at low to ~5390 cells/ml at high Cathepsin B/L expression." (PMID 33290397, 2020).
infection (continued). "In the presence of combined cathepsin B and D inhibitors at 100 μM but not at 50 μM, there was significant abrogation of the IL-32γ-induced reduction of intracellular burden at four days after infection." (PMID 25887904, 2015). "Moreover, although the CTSB puncta (red) increased after infection, the LAMP1-CTSB colocalization (yellow puncta) was significantly reduced in infected cells, compared with high colocalization in control cells, indicating that most of elevated cytosolic CTSB is extra-lysosomal at 12 hpi." (PMID 41277866, 2026). "This secretion is not specific to cathepsin B but rather is observed for several lysosomal proteins, which show unchanged intracellular abundance, including cathepsin D. This is likely a host response to infection rather than an active pathogenesis mechanism employed by C. burnetii." (PMID 40274809, 2025). "Macrophages were infected with H37Rv in the presence or absence of CA074-Me, a potent inhibitor of CTSB activity and in certain conditions other cathepsins, and mature IL-1β as well as cleaved caspase-1 were measured in supernatants at 6 and 24 h after infection." (PMID 29977244, 2018). "The analysis showed that neither the caspase-1 inhibitor YVAD, the cathepsin B inhibitor CA-074Me, nor the pan-caspase inhibitor ZVAD had any significant effect on DNA fragmentation, loss of mitochondrial potential or compromised plasma membrane integrity after two days of infection." (PMID 21637850, 2011). "Cathepsin B was shown to cleave the fusion protein in a cell-free system into two fragments but the smaller of these fragments migrated slower than fragments produced during the cleavage that occurs in infection, suggesting that the fusion protein was not cleaved at the correct size." (PMID 19619315, 2009). "We found that inhibition of ERK1/2, serine proteases and cathepsin B, but not p38, NF-κB and PKC, resulted in significantly lower IL-1β release compared to DMSO treated cells after CFT073 infection at MOI 1 for 6h." (PMID 34944029, 2021). "Although the E-MLV infection requires cathepsin B, the inhibitor does not attenuate HIV-1 Env-mediated infection." (PMID 26834711, 2015). "The CD4-TLR4 transfection did not affect the CD4-independent infection in TE671 and HeLa cells, in which cathepsin B was originally expressed at a high level." (PMID 21541353, 2011). "But when 293T cells were treated with CA-074Me at a lower concentration, cathepsin B activity in the treated 293T cells was not affected and the CD4-independent infection was not enhanced." (PMID 21541353, 2011). "A synthetic cathepsin B inhibitor, CA-074Me, also enhanced the CD4-independent mNDK vector infection in HeLa cells, but did not affect the CD4-dependent infection." (PMID 21541353, 2011). "Furthermore, infection of CTSB-overexpressing cell lines with C. burnetii led to a reduction, though not a complete absence, in cathepsin B." (PMID 40274809, 2025). "Because the endosome acidification inhibitors much less efficiently attenuated cathepsin B activity than CA-074Me, the endosome acidification inhibitors could not enhance the CD4-independent infection." (PMID 21541353, 2011). "Despite the fact that cell death involved plasma membrane permeabilization and coincided with IL-1β release, we conclude that necrosis induced upon infection of human macrophages with virulent Mtb secreting ESAT-6 over several days is independent of caspase-1 and cathepsin B." (PMID 21637850, 2011).
neurodegenerative disease (36 papers, 2015 to 2026). A disorder of the central nervous system characterized by gradual and progressive loss of neural tissue and neurologic function. "Despite CTSB’s positive association with exercise and cognition, it is also implicated in neurodegenerative disease pathogenesis." (PMID 40407975, 2025). "Muscle‐secreted protease Cathepsin B (Ctsb) is linked to memory in animals and humans, but has an unclear role in neurodegenerative diseases." (PMID 41047763, 2025). "Cathepsin B is a lysosomal cysteine protease implicated in the pathology of several neurodegenerative diseases, most notably AD in which it has been shown to contribute to increased Aβ load, yet also offers potential neuroprotective and anti-amyloidogenic properties." (PMID 32804976, 2020). "Previous research has demonstrated the involvement of microglial CTSB in driving neurodegenerative diseases primarily through neuroinflammation induction." (PMID 39958993, 2025). "Although irisin and CTSB have been implicated in adult hippocampal neurogenesis in mice, further studies are required to establish their role in improving cognition and memory, and whether they would be beneficial for neurodegenerative diseases such as AD in humans." (PMID 39898049, 2025). "In this section, we focus on two well-studied myokines, irisin and cathepsin B (CTSB), and their effects on neurodegenerative diseases." (PMID 40933823, 2025). "In neurodegenerative diseases and traumatic brain injury, lysosomal membrane permeabilization (LMP) can occur, causing CTSB to translocate to the cytoplasm." (PMID 39736788, 2024). "Intriguingly, calpain-1 had been reported to exhibit coordinated proteolytic actions with cathepsin B (CTSB) in neurodegenerative disease." (PMID 38725007, 2024). "High levels of CTSB are also found in neurodegenerative diseases, which indicates CTSB plays an important role in central nervous system diseases." (PMID 37307830, 2023). "CTSB is a potential therapeutic target for neurodegenerative diseases such as AD." (PMID 39286235, 2024). "Their recently identified role in lysosomal degradation of α-syn implies that CtsB/L activation may present a common approach to maintain lysosomal function and to prevent/ameliorate neurodegenerative diseases." (PMID 27902765, 2016). "Our findings implicate that enhancing the activity or levels of CtsB/L could provide a promising and a common strategy for maintaining lysosomal function and for preventing and/or treating neurodegenerative diseases." (PMID 27902765, 2016). "Notably, elevated CTSB levels are found in plasma, serum, and CSF in individuals with neurodegenerative diseases, including AD, where higher CTSB levels correlate with worse cognitive function as measured by the Mini-Mental State Examination (MMSE) [1097, 1100]." (PMID 40407975, 2025). "In summary, while CTSB appears beneficial in the context of exercise, promoting neurogenesis and cognitive improvements, it may also drive degenerative processes in neurovascular aging and neurodegenerative disease." (PMID 40407975, 2025). "In the tumor microenvironment, cathepsins regulate tissue protease functions through inflammatory mediators, CTSB, for example, is associated with immune cell infiltration and immunosuppression, while the interaction of CTSX and γ-enolase affects neuroinflammatory and neurodegenerative diseases." (PMID 39736788, 2024). "Neuronal caspase-1 from inflammasome and cathepsin B are key enzymes mediating neuroinflammation in AD, therefore, revealing new molecules to modulate these enzymes may be an interesting approach to treat neurodegenerative diseases." (PMID 36286438, 2022). "Our findings implicate that enhancing the activity or levels of CtsB and/or CtsL could provide a promising and a common strategy for maintaining lysosomal function, clearance of the aggregation prone proteins and for preventing and/or treating neurodegenerative diseases." (PMID 27902765, 2016).
neurodegenerative disease (continued). "In humans, plasma levels of CTSB have been shown to weakly correlate to fitness and memory score, but whether this leads to improvements in cognition and memory or would have any therapeutic benefit in neurodegenerative diseases such as AD has not been explored yet." (PMID 32998245, 2020).
cardiovascular diseases (17 papers, 2010 to 2025). "In this comprehensive review, we provide an in‐depth understanding of the role of CTSB in a range of cardiovascular diseases, elucidate its underlying mechanisms of action, and explore its practical applications within the context of disease progression." (PMID 39248527, 2024). "CTSB plays a central role in extracellular matrix remodeling and is associated with the development of cardiovascular diseases." (PMID 37576397, 2023). "Our results demonstrated that Cathepsin B is one of the important mediators of TMAO-induced endothelial injury, Cathepsin B may be a therapeutic target for treatment or prevention of endothelial injury and associated cardiovascular diseases." (PMID 37175227, 2023). "Nevertheless, a growing body of recent research has begun to unveil the intricate involvement of CTSB in cardiovascular diseases." (PMID 39248527, 2024). "The literatures have underscored the potential of circulating CTSB as prognostic biomarkers for cardiovascular disease." (PMID 39248527, 2024). "Among these associated protein-coding genes, MMP1, CTSB, POMC, RETN, and IL6R are known to be associated with SCAD or other cardiovascular diseases." (PMID 35425820, 2022). "Moreover, a growing body of scholars has identified the significant involvement of CTSB in cardiovascular diseases." (PMID 39248527, 2024). "The expression or activity change of CTSB in cardiovascular disease." (PMID 39248527, 2024). "However, our knowledge of CTSB in cardiovascular disease is still in the early stage." (PMID 39248527, 2024).
bacterial infection (12 papers, 2012 to 2025). "Cathepsin family members have been found in other mollusc species, including the Pacific abalone, Haliotis discus hannai, in which cathepsin B was found to be upregulated after bacterial infection." (PMID 40136550, 2025). "Nevertheless, the specific immunological participation of CTSB in immune responses to bacterial infection remains to be explored." (PMID 40422803, 2025). "Overall, these findings suggest that the CTSB genes in black rockfish might show essential functions in the host defense of teleosts against bacterial infections, providing valuable insights for further investigations into the immune mechanism of teleost CTSB." (PMID 40422803, 2025). "Moreover, cathepsin B was also enhanced in the olive flounder following immersion in a suspension of Flavobacterium columnare, which suggested that cathepsin B regulation is an indispensable component of the immune responses during bacterial infections." (PMID 30404247, 2018). "Moreover, the increased expressions of both CTSB and VAMP8 are associated with inflammatory and bacterial infection processes, which may indirectly reflect the dysbiosis of pulmonary immunity and microbiota triggered by ammonia exposure." (PMID 37250049, 2023). "Thus, the changes in the expression levels of CTSB might vary according to the type of pathogen and host response, and it was relatively common for the expression level of cathepsin genes to be induced after bacterial infection." (PMID 40422803, 2025).
neurological diseases (12 papers, 2013 to 2025). "However, cathepsin B in CSF from patients has been reported to be associated with neurologic diseases." (PMID 29479521, 2018). "Studies have shown that Cathepsin B gene knockdown can exert a neuroprotective effect, ameliorating behavioral deficits and pathological damage in neurological disease models." (PMID 38538614, 2024). "Similarly, as in humans, CTSB levels are increased in animals modeling neurologic disorders, and as shown in 12 studies, its deletion leads to significant improvements in behavioral deficits and neuropathology in these animal models." (PMID 39064733, 2024). "It was demonstrated that SAA might play an important role in the pathogenesis of neurological disorders by up‐regulating the expression of the cytokine interleukin‐1β (IL‐1β), which is mediated by the Nod‐like receptor protein 3 (NLRP3) inflammasome, cathepsin B, and caspase‐1." (PMID 34018701, 2021).
kidney diseases (10 papers, 2016 to 2025). "Further studies in order to validate total renal volume, cortical volume, and urinary activity of N-acetyl-β-d-glucosaminidase and cathepsin B as early indicators of long-term risk of renal diseases are needed." (PMID 30925803, 2019). "Possible diagnostic efficiency of renal volume, cortical volume, N-acetyl-β-glucosaminidase, and cathepsin B activity as risk factors for renal disease in later life of GDM neonates was evaluated by assessing the corresponding AUCs." (PMID 30925803, 2019). "LMP and the leakage of CTSB are also associated with necroptosis-induced kidney disease." (PMID 40129990, 2025). "In this review, we outline the fundamental mechanisms by which CTSB triggers different types of PCD in several kidney diseases and discuss the function of CTSB in various segments of the kidney." (PMID 40129990, 2025). "Like in the glomerulus and tubules, lysosomal CTSB can also participate in protein degradation in the collecting ducts, alleviating kidney disease by regulating autophagy." (PMID 40129990, 2025). "Several recent studies suggest that different types of PCD mediated by CTSB play key roles in kidney diseases." (PMID 40129990, 2025). "In the kidney, CTSB plays an irreplaceable role in mediating/regulating the induction of kidney diseases by inducing different types of PCD." (PMID 40129990, 2025). "In the future, an increasing number of new technologies will be used to target CTSB, opening a new chapter in the treatment of many diseases, including kidney diseases." (PMID 40129990, 2025). "In the future, more functions and the therapeutic potential of CTSB in kidney diseases will be revealed, providing scholars with new strategies and methods and demonstrating its significant value in the field of renal diseases in modern medicine." (PMID 40129990, 2025). "In kidney diseases, when CTSB is inhibited, autophagy flux decreases, which in turn leads to a decline in renal function." (PMID 40129990, 2025). "CTSB has received the most attention in the study of renal tubules, as it is involved in the occurrence of various kidney diseases in renal tubules." (PMID 40129990, 2025). "Different types of PCD are intricately linked, and CTSB, as one of the common mediators of different types of PCD, plays a key role in a variety of kidney diseases." (PMID 40129990, 2025). "Here, we focus on elucidating the mechanisms by which CTSB induces kidney disease through different types of PCD pathways." (PMID 40129990, 2025). "An increasing body of evidence suggests that CTSB induces the occurrence of kidney diseases through multiple cell death pathways." (PMID 40129990, 2025). "Numerous studies have demonstrated that LMP and CTSB are involved in the pathogenesis of kidney diseases." (PMID 36713420, 2022). "The important role of cathepsin B in renal disease progression was demonstrated recently showing that cathepsin B knockout mice were more resistant and recovered faster after glomerular damage upon podocyte injury induced by nephrotoxic serum." (PMID 31368174, 2019). "CTSB can be transported from lysosomes to the nucleus, where it can cause nuclear oxidative damage or induce the peroxidation of polyunsaturated fatty acids through the MMP-ROS axis, thereby triggering ferroptosis and the onset of kidney diseases." (PMID 40129990, 2025). "Moreover, we explore the possibilities and prospects of using CTSB as a therapeutic target for kidney diseases." (PMID 40129990, 2025). "CTSB, a key mediator, has been shown to play an important role in kidney disease." (PMID 40129990, 2025). "In addition, the CTSB protein has attracted increasing attention as a therapeutic target for diseases, and we further explore the role of CTSB in the treatment of kidney diseases." (PMID 40129990, 2025). "Inhibitors/drugs targeting CTSB or CTSB-related pathway for kidney disease therapy." (PMID 40129990, 2025).